CD47 (CD47 molecule)
Diseases named in the same sentence as CD47 in open-access papers (continued):
Sharing a sentence is not in itself a finding about the gene and the disease.
tumor (continued). "A well-characterized mechanism of immune evasion by tumor cells is the up-regulation of the antiphagocytic (“don’t eat me”) surface protein CD47 which binds to its cognate receptor SIRPα on phagocytic cells inhibiting its phagocytic activity." (PMID 30602457, 2019). "Flow cytometry (FACS) analysis of a dissociated fresh ATC indicated strong surface CD47 expression in the CD45− cell fraction containing the tumor cells." (PMID 30938231, 2019). "Anti-CD47 antibodies that increase phagocytosis of tumor cells are currently being tested in clinical trials of patients with leukemia." (PMID 31337788, 2019). "The challenge of CD47 therapy is thus to address the antibodies to the tumor site to reduce toxicity." (PMID 31544819, 2019). "CD47 is expressed by tumor cells and interacts with the signal regulatory protein-α (SIRPα, also known as SHPS1) expressed on the surface of phagocytic cells, such as macrophages and dendritic cells." (PMID 31878087, 2019). "CD47 is an immune checkpoint molecule that downregulates key aspects of both the innate and adaptive anti-tumor immune response via its counter receptor SIRPα, and it is expressed at high levels in a wide variety of tumor types." (PMID 31276567, 2019). "M2 macrophages (CD11b/F4/80/CD206+) demonstrated very little increase in tumor phagocytic activity in the presence of CD47 antibody." (PMID 30674867, 2019). "Nevertheless, recent discoveries showing that hypoxia negatively impacts the tumor immune response by modifying the expression of main immune checkpoints (e.g., PD-L1, CD47, PD-1, HLA-G...) provide a major opportunity for innovative combination approaches." (PMID 31540045, 2019). "Various studies have shown that the depletion of CD47 expression on cancer cells using either siRNA31,32 or genetic editing has proven effective in slowing down tumor growth and enhancing phagocytosis by macrophages." (PMID 31882679, 2019). "To investigate if tumor-expressed SLAMF7 was a requisite for phagocytosis of DLBCL cells upon CD47 targeting, we generated type 1 macrophages (MØ) as the prototype pro-inflammatory macrophage subtype associated with anti-cancer activity." (PMID 30710089, 2019). "Our study demonstrated that anti-CD47 treatment led to changes in the tumor microenvironment with increased pro-inflammatory macrophages that exhibit anti-tumor effect, while reduced anti-inflammatory macrophages that are associated with immunosuppression." (PMID 31771616, 2019). "Investigating the effect of the myeloid checkpoint inhibitor anti-CD47 we found that macrophages and microglia respond by phagocytizing tumor cells." (PMID 30602457, 2019). "Based on this evidence, several clinical trials are now being performed with anti-CD47 mAbs or CD47-Fc fusion proteins for the treatment of different tumor types, also in combination with anti-PD-1 therapy." (PMID 31878087, 2019). "Tumor volumes and weights, the frequency of DP macrophages in tumors, and the blocking of CD47 on GFP-expressing 8505C cells were comparable to conditions using parental 8505C cells." (PMID 30938231, 2019). "When applying a macrophage-negative gate (CD11b−/F4/80−) to exclude phagocytic tumor cells, we found 8% baseline tumor cell death in the presence of control antibody and 20% tumor cell death in the presence of CD47 mAb." (PMID 30674867, 2019). "In double-transgenic ATC mice, CD47 was expressed on tumor cells, and blocking CD47 increased TAM frequencies." (PMID 30938231, 2019). "By stratifying patients based on the expression of CD47 in the tumor, we observed that samples with high CD47 levels have a significant increase in immune score as compared to samples with low CD47 expression." (PMID 31277366, 2019). "We postulate that macrophage‐mediated phagocytosis of tumor cells in the presence of CD47 mAb supports macrophage‐activating effects of doxorubicin." (PMID 31376208, 2019). "Inhibiting CD47 was an effective method of suppressing tumor stemness even at high levels in CD133+ cells." (PMID 30741466, 2019).
tumor (continued). "Delivery of the anti-CD47 nanobody by tumor-colonizing bacteria increased activation of tumor-infiltrating T cells, resulting in tumor regression and suppression of metastases." (PMID 31370301, 2019). "Similar to CD47, tumour intensity of IDO1, a broadly studied immunosuppressive molecule, was used to group the samples into two categories." (PMID 31358801, 2019). "In summary, these data indicate that anti-CD47 treatment changes the intratumoral Treg cluster to blunt its inhibitory effect on the tumor response to the treatment." (PMID 31771616, 2019). "Upon binding to CD47 on tumor cells, the cytoplasmic tail of SIRPA becomes tyrosine-phosphorylated, and SHP-1 and SHP-2 phosphatases are recruited and activated, initiating dephosphorylation of downstream substrates." (PMID 30726215, 2019). "To investigate the anti-tumor effect of CD47 and PD-L1 combination treatment, we transplanted Panc02 and MPC-83 cells to C57BL/6 and KM mice." (PMID 31771616, 2019). "Once again, tumor immunology has led the way, with anti-CD47 Abs already in clinical trials, and showing clinical promise by way of dampening a “don't eat me” signal that otherwise spares tumor cells from destruction by monocytes and macrophages." (PMID 31379822, 2019). "Work in the Weissman lab at Stanford has for the first time demonstrated that anti-cancer activity from the innate immune system can be activated via blockade of the immune-suppressive cell surface molecule CD47 expressed on tumor cells." (PMID 31695797, 2019). "In this context, we found for the first time that the unsustainable efficacy of anti-angiogenic therapy was resulted from their ability to upregulate CD47 expression in tumor microenvironment conferring NSCLC resistant to anti-angiogenic therapy." (PMID 31829270, 2019). "In contrast, comparable to VEGFR1-Fc monotherapy, anti-angiogenic therapy in combination with CD47 blockade inhibited tumor regrowth and resulted in a low tumor burden." (PMID 31829270, 2019). "The primary aims of this research were to study the alterations in the immune compartment in response to a tumor upon vaccination with CD47-depleted syngeneic cells." (PMID 31882679, 2019). "CD47 expressed on tumor cells interacts with the receptors on M1-like TAMs and thus impairs their phagocytic activity." (PMID 31771653, 2019). "CD47 mAb-treated MNNG/HOS tumors showed significantly reduced tumor flux (p = 0.002) compared to control antibody-treated tumors." (PMID 30674867, 2019). "Given that CD47 is widely expressed on normal cells, what is the mechanism of this tumor selectivity?" (PMID 32038992, 2019). "ADCP elicited by targeting the CD47-SIRPα axis resulted in functional skewing of mouse macrophages towards an M1-like phenotype in tumor models, thus contributing to antitumor immune responses." (PMID 31805946, 2019). "We show that even in the absence of phagocytizing macrophages (Ccr2RFP/RFP), microglia are effector cells of tumor cell phagocytosis in response to anti-CD47 blockade." (PMID 30602457, 2019). "Initially, they aim to develop new tumor-targeted drugs to selectively block key innate and adaptive immune checkpoints, such as PD-1, TIM-3, and CD47, in the tumor micro-environment." (PMID 31554176, 2019). "Our data indicate that CD47 targeting induces compartmental remodeling of tumor-infiltrating immune cells of the TME in PDAC." (PMID 31771616, 2019). "By stratifying patients based on the expression of CD47 in the tumor, we observed that patients with high levels of CD47 have a significant increase in immune score as compared to patients with low levels of CD47." (PMID 31277366, 2019). "The CD47-SIRPα axis is a myeloid specific ICB that inhibits phagocytosis of tumor cells by macrophages and other myeloid cells." (PMID 31402908, 2019). "Fluorescence-activated cell sorting (FACS) and immunoblot analysis showed that tumor cells were the primary source of CD47 increased cells in NSCLC." (PMID 31829270, 2019).
tumor (continued). "Another recent approach to deliver siRNAs against oncogenic KRASG12D to PDAC tumours is using fibroblast-derived exosomes, termed iExosomes, which maintain CD47 expression and hence show increased bioavailability and tumour uptake." (PMID 30396902, 2019). "Since MNNG/HOS intratibial tumors spontaneously metastasize to the lungs, we compared the tumor burden of lung metastasis in mice treated with doxorubicin plus CD47 mAbs to that of control groups." (PMID 31376208, 2019). "CD47 is a membrane protein that functions as an anti-phagocytic cell surface ligand that blocks macrophages from destroying tumor cells." (PMID 30876441, 2019). "Combining CD47 mAb with doxorubicin reduced the tumor flux 7‐fold compared with doxorubicin only and fourfold compared with CD47 mAb therapy only." (PMID 31376208, 2019). "In brief, these data showed that CD47 was up-regulated by anti-angiogenic therapy in a tumor cell-specific manner." (PMID 31829270, 2019). "In summary, our work provides evidence that the “don't eat me” signal CD47 is expressed on human ATC to prevent TAM-mediated tumor phagocytosis." (PMID 30938231, 2019). "Here, we showed that CD47 can be employed as a vaccine target to suppress tumor growth and to increase immune infiltration in solid tumors." (PMID 31882679, 2019). "CD47 on tumor surfaces acts as a “don't eat me” signal and the up-regulation of this antiphagocytic signal enable tumor cells to escape from NK and DC cells while avoiding innate and adaptive immune response." (PMID 31754376, 2019). "A more unexpected, but very informative observation in this study was the extreme downregulation of cell surface CD47 by the tumor cells after vaccination with irradiated CD47−/− cells." (PMID 31882679, 2019). "Tumor cells overexpress CD47 on their surface as a defense mechanism to blindside the host’s immune defense systems." (PMID 31882679, 2019). "CD47 is a highly expressed tumor epithelial extracellular ligand that is detected by the macrophage SIRPα receptor." (PMID 32082375, 2019). "Using syngeneic models, we and others demonstrated that the anti-tumor efficacy of targeting CD47 requires both innate and adaptive immune activation for breast and colorectal cancer, melanoma, and B cell lymphomas." (PMID 31276567, 2019). "We observed that tumor cells receiving combination treatment showed marked increase of phagocytosis compared with doxorubicin (3.6‐fold, P < 0.0001) or CD47 mAb treatments (1.7‐fold, P < 0.0001) both by confocal microscopy and by FACS." (PMID 31376208, 2019). "When using SIRPα-Fc to block the interaction between SIRPα and CD47, alone or in combination with rituximab, phagocytosis of tumor cells was differentially increased in the three Mo/MΦ subsets." (PMID 31611550, 2019). "Beyond its effects on phagocytes, anti-CD47 treatment was found to modulate the tumor microenvironment to be more permissive for anti-tumor T cells in preclinical models of head and neck squamous cell carcinoma." (PMID 30621125, 2019). "Genetic disruption or antisense suppression of CD47 enhances cytotoxic T cell killing of target tumor cells in vitro and suppresses tumor growth in vivo when combined with local tumor irradiation or cytotoxic chemotherapy." (PMID 31632920, 2019). "For example, Hu5F9-G4, the first humanized mAb to human CD47 increases the phagocytosis of tumor cells by macrophages in vitro and eliminates tumors in xenograft mouse models." (PMID 31921125, 2019). "This dual anti-tumour activity enhances the utility of CC2C6 as a single biologic therapeutic for targeting CD47-expressing tumours." (PMID 29748606, 2018). "Although CD47 protein was detectable on all specimens, it was significantly overexpressed in tumor tissue compared with normal tissue." (PMID 30525058, 2018). "The characteristic overexpression of CD47 on tumor cells also makes it a potential target for antibody-driven immunotherapy." (PMID 30533489, 2018).
tumor (continued). "CRT interacts with CD91 on macrophages and is required for phagocytosis of tumor cells following neutralization of the CD47/SIRPα interaction." (PMID 29988496, 2018). "Recently, the combination of tumor-targeting antibodies with SIRPα-CD47 blockade has provided promising clinical results, suggesting that increased phagocytosis of cancer cells is clinically relevant for treatment of hematologic cancers." (PMID 30400822, 2018). "An overexpression of the CD47 gene was found in CTCs from CRC patients as compared to corresponding primary tumor tissue, suggesting a potential survival advantage." (PMID 30200242, 2018). "Overexpression of CD47 has been reported on numerous solid and hematological human cancers, and blocking CD47 promotes macrophage activation, enhances tumor cell phagocytosis and prolongs survival in murine cancer models." (PMID 29868474, 2018). "In general, the CD47-SIRPα-mediated antiphagocytic signal allows tumor cells to evade immune surveillance." (PMID 29329591, 2018). "CD47 is a membrane protein overexpressed on tumor cells and considered as an innate immune checkpoint." (PMID 30400822, 2018). "CD47 is a tumour cell surface antigen that is currently the target of several clinical trials utilizing biologics aimed at neutralizing its function as an anti-phagocytic receptor." (PMID 29748606, 2018). "Tumor cells express CD47, which can interact with the macrophages' SIRPα transmitting a “don't eat me” signal to macrophages." (PMID 30525058, 2018). "Using mouse CD47-blocking biAbs in a syngeneic tumor model allowed us to evaluate the efficacy of tumor-directed blockade of CD47 in the presence of the CD47 antigen sink and a functional adaptive immune system." (PMID 31544856, 2018). "CD47 is a broadly expressed membrane protein on various tumor cells and plays an important role in self-recognition by which normal cells protect themselves from phagocytosis." (PMID 30525058, 2018). "Although both treatments were able to reduce tumor size, combination of anti-CD47 and anti-PD-L1 treatments showed the greatest reduction, thus increasing the survival of the animals more than either monotherapy." (PMID 30399174, 2018). "ALX148 binds CD47 from multiple species with high affinity, inhibits wild type SIRPα binding, and enhances phagocytosis of tumor cells by macrophages." (PMID 30133535, 2018). "Tumor cells that express CD47, a cell surface glycoprotein, inhibit phagocytosis by binding to its receptor, signal-regulatory protein (SIRP) alpha, situated on macrophages and other immune cells." (PMID 30213113, 2018). "The increased CD47 expression on cancer cells would also increase the chance of cancer cell survival and is sometimes responsible for new tumor masses and even tumor relapse." (PMID 30463284, 2018). "The mice were treated with 12 μg of CD-47 or control siRNA (0.6 mg/kg) along with LPH-NPs intravenously after the mice had a tumor volume of 50 mm3." (PMID 29861465, 2018). "A potential solution is tumor-directed blockade of CD47, which can be achieved with bispecific antibodies (biAbs)." (PMID 31544856, 2018). "In primary human bladder cancer, a marked expression of CD47 was seen in CD44+ tumor initiating cells (TICs) that escape phagocytosis." (PMID 30200242, 2018). "Increased expression in tumor cells of such signals, like CD47 and programmed death-ligand 1 (PD-L1), is proposed to be a mechanism through which cancer cells induce “don’t eat me” signals and evade immune detection by T cells." (PMID 29988496, 2018). "By engaging SIRPα, CD47 limits the ability of macrophages to engulf tumor cells, acting as a major phagocytic barrier." (PMID 29850495, 2018). "SIRPα binds with CD47 and delivers a “don’t eat me” signal for phagocytic cells to help tumor cells escape from immune clearance." (PMID 30105024, 2018).
tumor (continued). "Targeting PD-L1 degradation, inhibiting CD47 expression, and preventing Y239/Y240 ShcA phosphorylation by using specific drugs, should allow tumor immune suppression to be contrasted differently from PD1-PD-L1 inhibitors." (PMID 30213113, 2018). "We have previously demonstrated that selective targeting of CD47 on tumor cells can be achieved with anti-CD47/TAA biAbs with a low-affinity anti-CD47 arm and a high-affinity anti-TAA arm." (PMID 31544856, 2018). "A major effort is under way to use monoclonal antibodies directed against CD47, a “don’t eat me” signal expressed by selected malignancies, to promote tumor cell ingestion by macrophages." (PMID 29441073, 2018). "Targeted blockade of both CD47 and PD-L1 on tumor cells with a bispecific anti-PD-L1-SIRPα agent showed significantly enhanced tumor targeting and therapeutic efficacy comparing with monotherapy." (PMID 30577797, 2018). "We grew subcutaneous tumor xenografts in mice and then excised the tumors to evaluate the binding efficiency of CD47 SERS NPs on fresh tissue samples excised from the mice." (PMID 30463284, 2018). "Surface-enhanced Raman scattering (SERS) nanoparticles conjugated with CD47-specific antibodies were then assessed for tumor targeting efficiency in cell culture and xenograft models." (PMID 30463284, 2018). "Signal regulatory protein α is a myeloid-specific receptor of CD47, which is broadly expressed on many types of somatic cells including tumor cells." (PMID 30105024, 2018). "Monoclonal antibodies are employed to bind with CD47, resulting in increased phagocytosis and even tumor death." (PMID 30463284, 2018). "CD47 gene is upregulated in tumours that inhibit innate immune responses, including macrophage phagocytosis." (PMID 30587792, 2018). "In mice that did not receive ALX148, staining with labeled ALX148 revealed greater CD47 expression on tumor cells than on CD4+ cells from the spleen or tumor." (PMID 30133535, 2018). "Tumor cells were treated in vitro with our CD47 antibodies either alone or in combination with chemotherapeutics followed by assessment of ICD/DAMPs using flow cytometry and biochemical assays." (PMID 30400822, 2018). "The interaction of TSP-1 with CD47 was found to be important in multiple processes related to tumor growth." (PMID 32984773, 2018). "Depletion of CD8+ T cells diminishes the anti-tumor activity of mouse CD47 antibody in a syngeneic mouse model." (PMID 30062558, 2018). "We show here that CD47-targeting biAbs inhibited tumor growth in vivo, promoting durable antitumor responses and stimulating CD8+ T cell activation in vitro." (PMID 31544856, 2018). "Some studies have reported that macrophage phagocytosis of tumor cells mediated by anti-CD47 antibodies is a major effector of the immune system." (PMID 29329591, 2018). "Taken together, the dual anti-tumour activities of CC2C6 has the potential to maximize the therapeutic benefits for targeting CD47." (PMID 29748606, 2018). "RRx-001 was shown to downregulate CD47 and SIRPα expression on tumor cells and macrophages, respectively, and to promote the phagocytosis of high-expressing CD47 A549 tumor cells." (PMID 30400835, 2018). "Taken together, we have found that the overexpression of CD47 in EC protected tumor cells against phagocytosis by macrophages in vitro and promoted the progression of EC in vivo." (PMID 30525058, 2018). "These toxicities underscore the need to ensure that CD47 blockade activates immune responses against tumor cells while sparing normal healthy cells." (PMID 30133535, 2018). "In mice, higher doses of ALX148 led to increased tumor penetration, with more CD47 occupancy on tumor cells and tumor-infiltrating lymphocytes." (PMID 30133535, 2018). "Accumulating evidences show that the CD47-SIRPα signal participates in tumor immune evasion mediated by TAMs." (PMID 30525058, 2018).